XRCC4 (X-ray repair cross complementing 4)
Diseases named in the same sentence as XRCC4 in open-access papers (continued):
Sharing a sentence is not in itself a finding about the gene and the disease.
cancer (continued). "However, the direct regulatory mechanism linking O-GlcNAcylation to XRCC4 function in cancer cells remains unclear." (PMID 41513635, 2026). "In addition, we found the mRNA expression of XRCC4 was significantly overexpressed in other 15 of 25 types of human cancers, while was low expressed in KICH and PRAD compared to the normal tissues, the result was validated by the data from the paired comparison via Xiantao Academic." (PMID 36765282, 2023). "In this integrated bioinformatics analysis, we comprehensively investigated the features of XRCC4 in multi-faceted, including expression pattern, prognosis, clinical subtypes, genetic mutation, TME immune cell infiltration, function and signaling pathway and drug sensitivity across cancer types." (PMID 36765282, 2023). "FBXW7 facilitates NHEJ in a degradation-independent manner via K63-linked polyubiquitination of X-ray repair cross-complementing protein 4 (XRCC4) at lysine 286, implying that inactivating FBXW7 could be a potential strategy for improving the efficacy of radiotherapy in human cancers." (PMID 36694209, 2023). "Until now no study has focused on the association between XRCC4 and pan-cancer." (PMID 36765282, 2023). "Besides, XRCC4 depletion significantly sensitized cancer cells to chemotherapy and/or radiotherapy." (PMID 32258128, 2020). "XRCC4, which plays a role in both non-homologous end joining and completion of the V(D)J recombination, is among the genes that have been associated with various types of cancer." (PMID 31030479, 2019). "However, neither immunologic abnormalities nor susceptibility to cancer were part of the clinical phenotype of our XRCC4-mutant patients." (PMID 25872942, 2015). "However, the link between XRCC4 and O-GlcNAcylation in cancer remains unclear." (PMID 41513635, 2026). "Collectively, these findings demonstrate that O-GlcNAcylation of XRCC4 at Thr308 modulates the resistance of cancer cells to DNA DSB damage, dependent on XRCC4." (PMID 41513635, 2026). "X-ray repair cross-complementing protein 4 (XRCC4) is a key component of the NHEJ pathway, which plays a crucial role in chemoresistance and cancer cell survival." (PMID 41513635, 2026). "XRCC4 is particularly sensitive to bleomycin compared to other proteins in the NHEJ pathway, as shown by a substantial decrease in cancer cell survival rates in XRCC4 knockout cells." (PMID 41513635, 2026). "The assembly of the DNA Ligase IV (LIG4)–XRCC4 complex is essential for NHEJ fidelity, however, the regulatory mechanisms governing this complex in cancer remain poorly understood." (PMID 41462961, 2025). "For example, genetic alteration at the coding region of DNA repair gene XRCC4 increased the amount of ADAs in the HCC cells and change the sensibility of cancer cells on anticancer drug doxorubicin." (PMID 37711588, 2023). "Although XRCC4 has been suggested to play a role in modulating the immune system, direct experimental evidence on the interaction between cancer, with differential XRCC4 expression, and specific immune cell types, is lacking." (PMID 41139700, 2026). "Our findings contribute to elucidating the functions of XRCC4 and the role of abnormal XRCC4 in diseases, including cancers and MPD, and may help in developing XRCC4‐targeted drugs, such as radiosensitizers, for humans and cats." (PMID 35000298, 2022). "Only a limited number of studies have found a correlation between expression of LIG4, XRCC4, or XLF and cancer progression and patient outcomes, but a couple of studies have found that increased expression of these factors results in increased aggressiveness in tumors." (PMID 28684677, 2017). "Inversely, cancer cells, when XRCC4 expression was knocked down, would feature increasing sensitivity to doxorubicin compared with these without XRCC4 knockdown [IC50s (95% CI), 0.22 (0.18-0.26) vs. 0.62 (0.58-0.67) μM]." (PMID 29152133, 2017).
cancer (continued). "Since XRCC4 plays a central role in the repair of DSB by NHEJ, the presence of active XRCC4 in cells may decrease DSB-mediated apoptosis in cancer cells during radiotherapy." (PMID 24795863, 2014). "Consequently, the absence of XRCC4 jeopardizes cancer cell survival and proliferation due to impaired DNA DSB repair." (PMID 41513635, 2026). "Moreover, MEF2D binding activity to FANCD2, EXO1, and XRCC4 was significantly higher in cancer cells than in normal cells, and ARN3261 significantly reduced MEF2D binding activity to FANCD2, EXO1, and XRCC4 in cancer cells compared with normal cells." (PMID 35642638, 2022). "Taken together, SIK2 inhibition decreases PARP enzyme activity and the expression of FANCD2, EXO1, and XRCC4, suggesting that the combination of a SIK2 inhibitor and PARP inhibitor has the potential to increase the magnitude and duration of PARP inhibitor activity in patients with different cancers." (PMID 35642638, 2022). "Such induced lethality is not observed in XRCC4 single knockout cells or XRCC4/PARP1 doubly deficient cells, leading us to hypothesize that Pol θ might represent a promising target for killing NHEJ-deficient cancer cells exposed to G1 DNA damage." (PMID 33067475, 2020). "X-ray repair cross-complementing protein 4 (XRCC4), a non-homologous end-joining protein involved in DNA double-strand break repair, is highly expressed in human cancer cells and tissues." (PMID 41513635, 2026). "Furthermore, CXorf56 protein overexpression suppressed the recruitment of phospho-DNA-PKcs, XRCC4, and LIG4, indicating that CXorf56-Ku70 binding impedes the recruitment of downstream responders of Ku70 to DNA damage sites, forcing cancer cells to choose HR rather than NHEJ for DSB repair." (PMID 37156759, 2023).
tumor (37 papers, 2010 to 2026). "Studies have reported the associations between abnormal expression of XRCC4 and tumor susceptibility and radiosensitivity, but the potential biological mechanisms by which XRCC4 exerts effects on tumorigenesis are not fully understood." (PMID 36765282, 2023). "The knockdown of XRCC4 significantly attenuated the tumor growth relative to the control under the treatment of cisplatin, suggesting XRCC4 loss sensitizing cisplatin treatment in vivo." (PMID 36551554, 2022). "Univariate Cox analysis showed that the tumor stage, XRCC4, XRCC5, and XRCC6 were potential risk factors for the OS in patients with LUAD, while no such statistically significant genes were found in patients with LUSC (P < 0.05)." (PMID 34486486, 2021). "Our previous reports further displayed that the variants in the C terminal domain of XRCC4 protein were significantly related to progression characteristics of hepatocarcinoma such as tumor size, stage, grade, and differentiation." (PMID 29152133, 2017). "Recent several studies have shown that the genetic variants of XRCC4 involve in the process of hepatocarcinoma carcinogenesis and affects tumor survival." (PMID 29152133, 2017). "Like tumor grade, XRCC4 codon 247 polymorphism was an independent prognostic factor influencing the survival of DIA." (PMID 24378850, 2013). "This suggests that XRCC4 expression (including decreasing protein caused by structure change) might involve in tumor progression and angiogenesis." (PMID 29152133, 2017). "Like some known predictive markers such as tumor size, tumor stage, and microvessel density, XRCC4 expression was significantly associated with the prognosis of hepatocarcinoma, and the corresponding prognostic values were 1.63 (1.25-2.11) for OS and 1.55 (1.19-2.02) for RFS, respectively." (PMID 29152133, 2017). "A decreased ability of repairing damaged DNA due to the dysregulation of XRCC4 may result in genomic instability, genic mutation, and tumor formation." (PMID 29152133, 2017). "Furthermore, XRCC4 polymorphism was correlated with tumor dedifferentiation of DIA (r = 0.261, p < 0.01)." (PMID 24378850, 2013). "This suggests that the missense mutation at codon 247 of XRCC4 codon 247 might decrease DNA repair capacity and increase tumor risk." (PMID 24378850, 2013). "Because previous studies had shown that XRCC4 codon 247 polymorphism may modify tumor outcome, we analyzed the relationship between this polymorphism and DIA prognosis." (PMID 24378850, 2013). "Compared with XRCC4 Y66F mutant, XRCC4 WT tumor showed resistance to chemotherapy treatment; in contrast, LDHi treatment significantly diminished the differential response to chemotherapy." (PMID 41462961, 2025). "We next tested how the deletion of LTR10.XRCC4 affects tumor response to irradiation in a mouse xenograft model." (PMID 39018396, 2024). "While the difference seen in knockout tumors was modest, our results are consistent with previous studies showing how XRCC4 knockdown in tumor cells leads to increased sensitivity to radiation or chemotherapy drugs such as cisplatin." (PMID 39018396, 2024). "This is consistent with a previous study showing the role of XRCC4 in tumor cell survival following irradiation." (PMID 39018396, 2024). "The TIMER and the Tumor Immune Single Cell Hub (TISCH) online databases were used to explore the relationship between XRCC4 and tumor immune microenvironment." (PMID 36765282, 2023). "We used six datasets (BRCA_GSE176078, KICH_GSE159115, KIRC_GSE171306, LIHC_GSE146409, PRAD_GSE141445 and STAD_GSE134520) of the TISCH database to evaluate XRCC4 expressions in the tumor microenvironment related immune cells." (PMID 36765282, 2023).
tumor (continued). "The XRCC4 expression was significantly upregulated in 15 tumor types and downregulated in two tumor types compared with the normal tissues, most of which were validated by the results of Xiantao academic platform." (PMID 36765282, 2023). "We also demonstrated that knockdown of XRCC4 or treatment of the JNK inhibitor decreased cisplatin-resistant tumor growth in the xenograft mouse models, implying the clinical translation of targeting the cJUN-XRCC4 pathway in overcoming cisplatin resistance." (PMID 36551554, 2022). "Knockdown of XRCC4 or treatment of the JNK inhibitor led to the attenuation of cisplatin-resistant tumor growth in the xenograft mouse models." (PMID 36551554, 2022). "Our results indicated that the expression levels of XRCC5/6 were positively correlated, while those of XRCC4 were negatively correlated with tumor purity." (PMID 34486486, 2021). "Mechanistically, lncRNA SBF2-AS1 acting as a competing endogenous RNA (ceRNA) for miR-151a-3p, leads to the disinhibition of its endogenous target, XRCC4, which enhances DNA lesions repair in tumor cells." (PMID 33407894, 2021). "To investigate the correlation between XRCC4 expression and clinicopathological characteristics of hepatocarcinoma cases, we detected the expression of XRCC4 protein in tumor tissues using immunohistochemistry technique." (PMID 29152133, 2017). "The artificial amiR efficiently inhibited the expression of XRCC2 and XRCC4 genes, sensitizing human tumor cells to radiation-induced death." (PMID 24616890, 2014). "Furthermore, western blot also confirmed the aberrant expression of CTSL, CTSD, HSPA8, and XRCC4 in tumor tissues relative to paracancerous normal tissues." (PMID 41399382, 2026). "Finally, we conducted tumor xenograft assays on BALB/c nude mice to confirm the role of O-GlcNAcylation on XRCC4 at Thr308 in tumor development." (PMID 41513635, 2026). "Likewise, should a tumor develop in XRCC4 patient, therapy must be extremely cautious to avoid the morbidity associated with the acute toxicity of genotoxic treatments, as previously documented in a LIG4 patient." (PMID 40114033, 2025). "This difference in initial tumor volume may be due to the fact that the LTR10.XRCC4 knockout also reduced expression of VCAN, a gene that is often associated with tumor growth and establishment." (PMID 39018396, 2024). "Irradiation inhibits the growth of tumors derived from HCT116 cells; therefore, we tested whether reducing XRCC4 expression by deleting LTR10.XRCC4 affects tumor growth inhibition by irradiation." (PMID 39018396, 2024). "Both VCAN and XRCC4 have been reported to be regulated by MAPK/AP1 signaling in tumor cells, but the specific regulatory elements driving tumor-specific expression of these genes are unknown." (PMID 39018396, 2024). "However, LTR10.XRCC4 knockout tumors showed more significant overall tumor growth inhibition by irradiation, including at earlier time points." (PMID 39018396, 2024). "This allows for potent promotion of XRCC4 nuclear translocation and robust enhancement of DNA repair, even when tumor cells have constrained conventional SUMOylation sites, due to continuous replenishment from extracellular vesicles-derived circBIRC6 in the TME." (PMID 38012734, 2023). "Besides that, XRCC4 has been proven to be negatively related to the overall survival (OS) and tumor recurrence-free survival (RFS) in hepatocarcinoma." (PMID 36765282, 2023). "All groups displayed equivalent fluorescence intensity levels at the onset of treatment, suggesting that the XRCC4 mutation did not affect tumor growth." (PMID 38012734, 2023). "Therefore, identifying genes that are functionally similar to XRCC4/5/6 will aid in the discovery of other DNA repair target genes, thereby expanding the therapeutic options for tumor treatment.." (PMID 34486486, 2021). "Taking together, targeting XRCC4 could contribute to the prediction of radiosensitivity of specific patients and the sensitization of tumor cells." (PMID 30842344, 2019).
tumor (continued). "This suggests that the highly expressed XRCC4 may protect tumor cells from apoptosis when endogenous DNA damages are generated by their excessive proliferation." (PMID 29415984, 2018). "Decreasing expression of XRCC4, independent of the clinicopathological features of hepatocarcinoma, increased 1.55-times tumor-recurrence risk and 1.63-folds mortality risk." (PMID 29152133, 2017). "Interestingly, higher expression of XRCC4 has previously been reported in tumor samples isolated from patients with MM." (PMID 25790254, 2015). "Since it is one of the ubiquitous NHEJ components, XRCC4 might be considered as a potential tumor suppressor gene in several types of carcinoma." (PMID 20920336, 2010). "In addition, multivariate Cox analysis demonstrated that the tumor stage, XRCC4, XRCC5, and XRCC6 could predict the tumor prognosis independent of other factors for the OS in patients with LUAD (P < 0.05)." (PMID 34486486, 2021). "However, tumor tissues with relatively intact retinal structure showed denser XRCC4 staining in the regions where UHRF1 is highly expressed, implying that UHRF1 expressed during tumorigenesis of retina may further promote the XRCC4 expression." (PMID 29415984, 2018). "Altogether, the aberrantly expressed signature genes (XRCC4, CTSL, CTSD, and HSPA8) is closely related to tumor malignant progression." (PMID 41399382, 2026). "By contrast, in the Met group, TFs related to tumor angiogenesis, metastasis and EMT, such as XRCC4, MYC and MAZ showed elevated activity 23–25." (PMID 41413734, 2025). "As XRCC4 involved in the DDR, it has the potential to be a biomarker for the sensitivity of tumor cells to chemotherapy and radiotherapy." (PMID 36765282, 2023). "In this regard, the main targeting components of DNA repair machinery such as RAD51, XRCC3, RPA‐1 in HR and XRCC4, KU70, KU80 in NHEJ can open a new window for treatment of the EC by sensitizing tumor cells to radiotherapy." (PMID 36147024, 2022). "For example, X-ray repair cross complementing 4 (XRCC4), a major factor for double-strand breaks (DSBs) repair, has recently been shown to be connected with TMZ resistance in tumor cells." (PMID 33407894, 2021). "This analysis revealed significant upregulation of five genes, (XRCC6, XRCC4, PRKDC, XRCC4, and PAXX) and downregulation of two (LIG4 and NHEJ1) NHEJ pathway genes, in tumor tissues compared to the normal tissues." (PMID 33195430, 2020). "Additional genes with potential tumor suppressor function that have been shown to be involved in MCPyV integration include PTPRG, GRWD1, and XRCC4." (PMID 32878339, 2020). "While both PARP1, XRCC4 and ERCC1 are related to tumor resistance and metastasis, the specific biological mechanism and the existence of a common mechanism of action between the three are unclear and need further study." (PMID 33184404, 2020). "PAXX was recently proposed to function as a NHEJ factor on the basis of its structural homology to XRCC4 and XLF, and the IR sensitivity of PAXX-depleted human tumour lines." (PMID 28051062, 2017). "We have found evidence suggesting that the genotypes of XRCC4 with codon 247 Ser alleles may be correlated with increased risk and poor prognosis for DIA, and that the decreasing NHEJ capacity may play an important role in the tumorigenesis of this type of tumor." (PMID 24378850, 2013). "The result showed that normal liver, breast, lung and renal had negative or medium XRCC4 IHC staining, but tumor tissues showed medium or strong IHC staining." (PMID 36765282, 2023). "Out of 11 genes associated with the non-homologous end joining, 4 (i.e., XRCC4, PRKDC, FEN1, and DCLRE1C) display significantly higher expressions in OS tumor samples than normal controls while DNTT has no detectable expression in normal controls." (PMID 35013466, 2022).